WDFY3 (WD repeat and FYVE domain containing 3)
Diseases named in the same sentence as WDFY3 in open-access papers:
WDFY3 is named in the same sentence as 38 diseases in open-access papers, as found by Europe PMC text mining. Sharing a sentence is not in itself a finding about the gene and the disease. The quoted sentences say what the papers report.
microcephaly (13 papers, 2016 to 2024). A congenital or acquired developmental disorder in which the circumference of the head is smaller than normal for the person's age and sex. "Surprisingly, in humans, proliferation defects result in both microcephaly due to ALFY mutation or macrocephaly due to WDFY3- (encoding for ALFY) haploinsufficiency, which has been associated with ASD." (PMID 38201307, 2024). "Although, WDFY3 pathogenic variants were reported to cause microcephaly or macrocephaly, the described fetus in this case had normal head circumference." (PMID 33898534, 2021). "The human gene WDFY3 is nearly identical to the gene that encodes the Alfy protein, and has been implicated in neurodevelopmental disorders such as autism and microencephaly." (PMID 27648578, 2016). "Through linkage analysis and whole exome sequencing, we demonstrated that dominantly inherited human congenital microcephaly with mild to moderate intellectual disability is caused by a mutation in hALFY (termed also WDFY3)." (PMID 27008544, 2016). "Indeed, one study of WDFY3 (MIM: 617485) germline variants has linked upregulation of the Wnt/β-catenin signaling to microcephaly and downregulation to macrocephaly with unclear molecular mechanism." (PMID 39168120, 2024). "A third canonical splice site variant was a de novo splice donor variant (c.2345 + 1G > A), predicted to be pathogenic, in the known microcephaly-associated gene, WDFY3 (OMIM #617520) in a foetus with congenital brain anomalies including small cerebellum seen on a pre-natal scan." (PMID 37946251, 2023). "At this stage, LoF WDFY3 will increase Wnt signaling and enhance symmetric cell division of apical progenitor cells (APCs) and hamper asymmetric cell division so that less neurons are produced, which will eventually lead to microcephaly." (PMID 39168120, 2024). "However, mutations in one of the MCPH genes, WDFY3, act in an autosomal dominant manner and are associated with MCPH18, characterized by microcephaly with mild to moderate intellectual disability." (PMID 36831309, 2023). "Furthermore, genetic screening has revealed a possible role for the human homolog WDFY3 as a genetic risk factor for intellectual and developmental disabilities (IDD), microcephaly and neuropsychiatric disorders." (PMID 27648578, 2016). "Variants in multiple genes regulating endosomal trafficking and/or fusion of secretory vesicles [such as SMPD4, WDFY3, TRAPPC4, RAB18, VPS13B, EXOC7, EXOC8, VPS11], have been associated with the occurrence of microcephaly, cerebral atrophy, and neurodevelopmental delay." (PMID 36538041, 2023). "Unlike WDFY3-associated macrocephaly where Wnt/β-catenin signaling was downregulated, Wnt/β-catenin signaling was enhanced for missense variants in ZNRF3 from the macrocephaly affected individuals, while decreased for the ZNRF3 missense variant from the microcephaly affected individual." (PMID 39168120, 2024).
autism (8 papers, 2017 to 2025). Persistent deficits in social interaction and communication and interaction as well as a markedly restricted repertoire of activity and interest as well as repetitive patterns of behavior. "WDFY3 is an autism risk gene and causative in a range of other often comorbid neurodevelopmental disorders, including neurodevelopmental delay, intellectual disability, and hypotonia." (PMID 35733184, 2022). "A key finding of our study is the identification of a genetic interaction between the homologs of two autism-associated genes, egl-19 and wdfy-3." (PMID 31805042, 2019). "As part of an ongoing effort to test autism-associated genes for roles in axon development, we identified a genetic interaction between egl-19(gof) and wdfy-3, a homolog of the autism-associated WDFY3 selective autophagy gene." (PMID 31805042, 2019). "The interaction between the Timothy syndrome mutation and wdfy-3 provides biological evidence for a role of selective autophagy in autism." (PMID 31805042, 2019). "Loss of Wdfy3 led to a regionally enlarged cerebral cortex resembling early brain overgrowth described in many children on the autism spectrum." (PMID 29312436, 2017). "In humans, WDFY3 is a recognized autism risk gene associated with macrocephaly." (PMID 35733184, 2022). "Alternatively, a weak loss of function in CACNA1C could synergize with a weak loss-of-function in WDFY3 to give rise to autism." (PMID 31805042, 2019). "Moreover, we find that egl-19 gain-of-function mutations interact genetically with a homolog of the autism-associated WDFY3 selective autophagy gene to disrupt axon development and alter behavior." (PMID 31805042, 2019). "Moreover, we have discussed genetic interactions suggesting that the LRK-1 ortholog of LRRK2 regulates axon development by functioning in a pathway with the ortholog of the WDFY3 selective autophagy protein (aka Alfy), which is encoded by an autism-associated gene." (PMID 40371391, 2025). "However, the rs1006737 risk variant could synergize with a gain-of-function risk variant in WDFY3 to contribute to autism." (PMID 31805042, 2019). "For example, several studies have demonstrated that WDFY3, AMBRA1, and PARK2 gene mutations manifest as autism-like symptoms and as mitophagy dysfunction." (PMID 37108406, 2023). "For example, WDFY3 is a candidate gene for autism because whole genome sequencing has found that 3 out of 6707 sequenced autism genomes contain a heterozygous de novo likely-gene-disrupting mutation in WDFY3." (PMID 31805042, 2019). "WD repeat and FYVE domain-containing 3 (WDFY3; also known as Autophagy-Linked FYVE or Alfy) is an identified intellectual disability, developmental delay and autism risk gene." (PMID 30054502, 2018). "Interestingly, decreased dendritic complexity in Wdfy3 mutant neurons agrees with findings in other ASD risk genes, has been observed postmortem in the hippocampi of autism cases, and may be a point of convergence between ASD and Rett syndrome." (PMID 35733184, 2022). "However, despite this association, it is not possible to determine if WDFY3 variants contribute to the cause of autism." (PMID 31805042, 2019). "Therefore, we hypothesize that the WDFY3 and LRRK proteins could function together to protect against autism." (PMID 40371391, 2025).
Intellectual disability (8 papers, 2016 to 2023). "Human WDFY3 mutation will result in neurodevelopmental disorders, such as intellectual disability, neurodevelopmental delay, and most frequently ASD associated with macrocephaly." (PMID 35733184, 2022). "Pathogenic WDFY3 variants caused mild to moderate neurodevelopmental delay and intellectual disability, most of which (8/13) were loss-of-function variant and putatively lead to haploinsufficiency." (PMID 33898534, 2021). "Since macrocephaly is more strongly related to ASD than to intellectual disability (ID) and many hcASD genes such as CHD8 and WDFY3 cause dysregulation of proliferation and brain overgrowth, what other fetal mechanisms are altered by excess proliferation that lead to an ASD outcome?" (PMID 29934544, 2019). "For instance, similar to WDFY3, mutations in DPP6, which encodes a dipeptidyl peptidase protein, cause autosomal dominant microcephaly in addition to intellectual disabilities, indicating that it may also be necessary to screen through heterozygous variants in patients." (PMID 33178111, 2020). "In addition, the dosage of WDFY3 is affected in a subset of individuals with a rare chromosome disorder known as 4q21 deletion syndrome [OMIM 613509], characterized by intellectual disabilities (ID), language impairment and congenital birth defects." (PMID 27648578, 2016).
Macrocephaly (5 papers, 2018 to 2024). Occipitofrontal (head) circumference greater than 97th centile compared to appropriate, age matched, sex-matched normal standards. "Depending on the specific allele, heterozygous WDFY3 loss in humans is typically associated with macrocephaly, a feature faithfully modeled in heterozygous and homozygous mutant mice." (PMID 35733184, 2022). "Furthermore, almost all their WDFY3 variants causing macrocephaly were truncating, suggesting WDFY3 haploinsufficiency as a pathomechanism for macrocephaly." (PMID 39168120, 2024). "We identified a potential novel risk gene (ZNF292), one novel gene with recurrent LGD DNMs (RALGAPB), as well as genes associated with macrocephaly (GIGYF2 and WDFY3)." (PMID 30564305, 2018). "In contrast, gain-of-function WDFY3 will abnormally decrease Wnt signaling and attenuate symmetric but enhance asymmetric cell divisions so that more neurons will be generated, which eventually leads to macrocephaly." (PMID 39168120, 2024).
Parkinson disease (3 papers, 2018 to 2026). A progressive degenerative disorder of the central nervous system characterized by loss of dopamine producing neurons in the substantia nigra and the presence of Lewy bodies in the substantia nigra and locus coeruleus. "Another key question for future investigation is the potential involvement of the WDFY3 gene in protecting against Parkinson’s disease and other neurodegenerative disorders." (PMID 40371391, 2025). "Deficits or pathogenic mutations in BEACH-containing proteins other than WDFY3 in humans are associated with bipolar disorder, schizophrenia, epilepsy, ASD, and neurodegenerative diseases, such as AD, ALS and Parkinson’s disease." (PMID 30054502, 2018). "Although WDFY3 gene has not been associated with Parkinson’s, the WDFY3 protein has been implicated in mitophagy, which is thought to be involved in Parkinson’s." (PMID 40371391, 2025). "Considering the genetic interactions between wdfy-3 and lrk-1 in C. elegans, we propose that the WDFY3 gene could be involved in protecting against Parkinson’s disease." (PMID 40371391, 2025).
Huntington disease (2 papers, 2023 to 2025). Huntington disease (HD) is a rare neurodegenerative disorder of the central nervous system characterized by unwanted choreatic movements, behavioral and psychiatric disturbances and dementia. "In addition, WDFY3 has been implicated in protecting against Huntington’s disease, suggesting that it can protect against neurodegeneration." (PMID 40371391, 2025).
pancreatic cancer (2 papers, 2023 to 2025). "Similar to LC3, we found that p62, WDFY3, and NQO1 were also strongly positive in ADM and pancreatic cancer cells." (PMID 37664430, 2023). "The present study revealed that p62, WDFY3, NQO1, and LC3 were positive in the fatty area, ADM, and pancreatic cancer cells." (PMID 37664430, 2023). "The high expression of autophagy-related proteins, such as p62, WDFY3, and NQO1, in acinar cells near pancreatic steatosis, especially in acinar-ductal metaplasia and pancreatic cancer cells, indicates a link between autophagy disruption, oxidative stress, DNA damage, and pancreatic cancer." (PMID 39991930, 2025).
atherosclerosis (1 paper, 2022). A disease characterized by the build-up of fatty material and calcium deposition in the arterial wall resulting in partial or complete occlusion of the arterial lumen. "Therapeutic activation of WDFY3 may represent a pro-efferocytotic therapy in atherosclerosis and other diseases related to defective efferocytosis." (PMID 36566259, 2022).
autism spectrum disorder (1 paper, 2016). A spectrum of developmental disorders that includes autism, and Asperger syndrome. "Furthermore, in autism spectrum disorder (ASD), rare de novo nonsense mutations within WDFY3 have been identified across two independent studies." (PMID 27648578, 2016).
autosomal dominant primary microcephaly (1 paper, 2016). Autosomal dominant form of microcephaly (disease). "Most recently, a missense mutation in WDFY3 has been linked to autosomal dominant primary microcephaly." (PMID 27648578, 2016).
depression (1 paper, 2021). "We detected high impact variants in genes previously implicated in depression (e.g. Gnat2), depression-like behavior (e.g. Prlr, Nlrp1a), other psychiatric disease (e.g. Pou6f2, Kdm5a, Reep3, Wdfy3), and responses to psychological stressors (e.g. Pigr)." (PMID 34285244, 2021).
glioma (1 paper, 2022). A benign or malignant brain and spinal cord tumor that arises from glial cells (astrocytes, oligodendrocytes, ependymal cells). "The forest plot shows that EPB41L4A.AS1, GDNF.AS1, HAR1A, LINC00237, SLC25A21.AS1, SNA13.AS1, and WDFY3.AS2 are the protective factors with HR < 1, while LINC00092, LINC00265, LINC00339, LINC00665, PAXIP1.AS2, SNHG16, SNHG9 and SOCS2.AS1 are risk factors with HR>1 in glioma patients." (PMID 35273128, 2022).
retinal degeneration (1 paper, 2020). Degeneration of the retina. "Functionally, WDFY3 is associated with autophagy, an essential process for retinal cells to prevent the accumulation of phototransduction effector proteins, which is described to cause retinal degeneration, and a decrease of oxidative stress in retinal epithelial cells." (PMID 33302505, 2020).
schizophrenia (1 paper, 2016). A major psychotic disorder characterized by abnormalities in the perception or expression of reality. "WDFY3 resides on chromosome 4q21.23 and this region of chromosome 4 was suggested to harbor a genetic predisposition to ASD and to schizophrenia." (PMID 27648578, 2016).
Stroke (1 paper, 2023). Sudden impairment of blood flow to a part of the brain due to occlusion or rupture of an artery to the brain. "The upregulation of WDFY3 in the serum of CE stroke patients indicated an elevated selective elimination of β-sheet misfolded aggregates." (PMID 37305740, 2023).
Timothy syndrome (1 paper, 2019). "If EGL-19 and WDFY-3 do function together in a pathway, it is possible that the Timothy syndrome mutation induces excessive selective autophagy that causes a disruption of axon termination." (PMID 31805042, 2019).
neurodegenerative disease (4 papers, 2015 to 2026). A disorder of the central nervous system characterized by gradual and progressive loss of neural tissue and neurologic function. "Together, these findings demonstrate that impaired autophagy resulting from reduced Wdfy3 expression recapitulates key features of neurodegenerative disease at both early and later stages." (PMID 41935068, 2026). "Similarly, genetic mutations in autophagic receptors, such as p62, OPTN, NBR1, and ALFY/WDFY3, have often been associated with neurodegenerative diseases." (PMID 32397599, 2020).
psychiatric disorder (3 papers, 2017 to 2021). A disorder characterized by behavioral and/or psychological abnormalities, often accompanied by physical symptoms. "Further, Pou6f2, Kdm5a, Reep3, Wdfy3 have been implicated in psychiatric diseases such as autism and Pigr was found to be involved in response to psychological stress." (PMID 34285244, 2021). "Although the analyses conducted including meta, PRSs, DAPPLE provide little evidence to suggest that ADHD and OCD share common genetic etiologies, our eQTL analysis suggested a potential role for the WDFY3 gene in psychiatric disorders such as ADHD and/or OCD." (PMID 28386217, 2017).
neurodevelopmental disorder (2 papers, 2022 to 2026). A behavioral and cognitive disorder with onset during the developmental period that involves impaired or aberrant development of intellectual, motor, or social functions. "Loss of Wdfy3 in mice causes severe deficits in neuronal health, and pathogenic mutations in WDFY3 are associated with neurodevelopmental disorders in humans." (PMID 41935068, 2026).
infection (1 paper, 2024). The state of being infected such as from the introduction of a foreign agent such as serum, vaccine, antigenic substance or organism. "In support of this hypothesis, cells within the infected culture that controlled infection effectively (zero vRNA counts) achieved greater suppression of SQSTM1 and WDFY3 expression than cells that failed to control infection (1+ viral counts)." (PMID 38659941, 2024).
neurological disorders (1 paper, 2016). "Taken together, these data imply WDFY3 is a rare genetic risk factor for childhood neurological disorders." (PMID 27648578, 2016).
WDFY3 also shares sentences with these, for which no sentence is quoted: Primary microcephaly (4 papers); Neurodevelopmental delay (3); developmental delay (2); Parkinson’s (2); amyotrophic lateral sclerosis (1); Autosomal dominant microcephaly (1); breast carcinoma (1); cancer (1); Cerebral atrophy (1); Chédiak-Higashi Syndrome (1); chromosome disorder (1); epilepsy (1); frontotemporal dementia (1); prion disease (1); Rett syndrome (1); Sepsis (1); tumor (1).